PRL (prolactin)
Diseases named in the same sentence as PRL in open-access papers (continued):
Sharing a sentence is not in itself a finding about the gene and the disease.
Cognitive impairment (22 papers, 2012 to 2026). Abnormal cognition is characterized by deficits in thinking, reasoning, or remembering. "Cognitive deficit in schizophrenic patients has been linked to imbalances in serum levels of cortisol and prolactin." (PMID 34576069, 2021). "Prolactin levels have also been linked to cognitive impairment." (PMID 34576069, 2021). "A previous study indicated that high and low levels of PRL were related to cognitive impairment in tasks involving processing speed and verbal recall in older men and that higher PRL levels were related to poorer working memory and verbal ability." (PMID 38346717, 2024). "Our previous studies established the PrL region as a target for DBS to effectively attenuate age-related cognitive impairments." (PMID 36818556, 2023). "Mechanistically, the failure of PrL DBS to rescue cognitive deficits in RG108-infused animals, despite the unaffected anxiolytic effects, suggests that hippocampal DNMT activity specifically drives the cognitive enhancements by PrL DBS." (PMID 36818556, 2023). "We showed that PrL DBS with MET treatment elicited more robust memory rescue in our aged animal model with cognitive impairment." (PMID 36818556, 2023). "Oral ingestion of DMT after drinking ayahuasca decoction causes decreased motor activity and other neurochemical effects leading to cognitive impairment, increased prolactin and cortisol levels, and decreased lymphocyte counts." (PMID 37375778, 2023). "The aim of this study was to identify possible cognitive impairment and to further explore the correlation between these indices and prolactin (PRL) levels, based on the control of tumor size." (PMID 36009154, 2022). "Altogether, deactivation of PrL appears to be associated with affective deficits associated with persistent pain and inhibition of hyperactivity of amygdala neurons reverses the deactivation of PrL and concomitant cognitive deficits." (PMID 32414089, 2020). "In the present study, we found that dietary intake of 0.1% GF food pellets during the juvenile and adolescent stages of offspring after MIA prevented cognitive deficits and reduction of PV-IR in the PrL of the mPFC at adulthood after MIA." (PMID 29391571, 2018). "Using different behavioral models, we confirmed that aged rats exhibited cognitive impairment in memory retention test 24 h after training, and overexpression of PKMζ in the PrL rescued cognitive impairment in aged rats." (PMID 26926225, 2016). "Many studies reported an association between elevated prolactin and cognitive impairment but did not specify how it affects cognitive function." (PMID 39361237, 2025). "Excessive PRL may inversely inhibit dopamine activity, leading to mild cognitive impairment (interference control)." (PMID 36009154, 2022). "Thus, possible role of prolactin on the relation between the pituitary volume and cognitive impairments should be further tested in an antipsychotic-naïve cohort." (PMID 30473669, 2018). "In conclusion, we found that the hypermethylation of PKMζ might impair the retention of LTM in aged rats, and environmental enrichment reversed cognitive impairment in aged rats probably by facilitating PKMζ DNA demethylation in the PrL." (PMID 26926225, 2016). "Additionally, prolactin levels and cognitive impairments were positively associated in some, yet not all studies." (PMID 40512752, 2025). "Previous research reported that PRL overproduction could lead to cognitive impairments." (PMID 34526949, 2021). "Therefore, patients with abnormally high PRL may have cognitive impairments due to brain structural damages." (PMID 34659078, 2021). "Therefore, loss of PV immunoreactivity in the PrL, but not IL, of mPFC of adult offspring might be associated with cognitive deficits in MIA offspring." (PMID 27824119, 2016). "Elucidating how MET and PrL DBS elicit their therapeutic effects on ameliorating DNA hypomethylation and cognitive deficits in aged animal models may yield translational insights." (PMID 36818556, 2023).
Cognitive impairment (continued). "However, activation of PrL GABAergic neurons seemed that they did not further inhibit the local glutamatergic neurons to aggravate cognitive impairments, but alleviated POD probably through other long-range projections as in HIP and amygdala." (PMID 36533179, 2022).
Hyperglycemia (21 papers, 2013 to 2025). An increased concentration of glucose in the blood. "The resistance may cause maternal hyperglycemia but the glucose level is maintained by the expansion of beta cells driven by prolactin and placental lactogen." (PMID 28361687, 2017). "The results of the blood tests we performed were as follows: fasting hyperglycemia and fasting insulin resistance were confirmed, with normal blood glucose and insulin response to glucose load; androgens, prolactin and cortisol levels were normal." (PMID 40710038, 2025). "In our study we were not able to measure prolactin levels, but the relationship between maternal prolactin and the resurgence of hyperglycaemia in women with previous GDM has been confirmed in previous studies." (PMID 38918525, 2024). "A direct adverse effect of maternal hyperglycaemia on PRL secretion has been proposed by some authors." (PMID 36769162, 2023). "The aberrant secretion of hormones including PRL, hPL and GH2 discussed previously can place pregnant women at an increased risk of hyperglycaemia, GDM and potentially other adverse outcomes of pregnancy." (PMID 37049394, 2023). "Her initial laboratory findings demonstrated hyperglycemia, hyperlipidemia, normal thyroid functions, low gonadotropin levels, and severe prolactin elevation with macroprolactin absence (serum prolactin > 40000 mIU/L, normal ranges: 33.36–580.80)." (PMID 23762662, 2013). "The results of the blood tests we performed were as follows: the presence of fasting hyperglycemia was confirmed; fasting insulin resistance and normal glycemic and insulin responses to glucose load were found; and androgen, prolactin and cortisol levels were normal." (PMID 40710038, 2025). "PRL is produced and released by fat cells and glands in normal human breasts, as well as by macrophages in the adipose tissue in response to inflammation and hyperglycemia." (PMID 32477263, 2020). "PRL may be secreted by macrophages in the adipose tissue in response to inflammation and hyperglycemia, promoting the formation of adipose and inhibiting the decomposition of lipid in the adipose tissue." (PMID 32477263, 2020). "The transiently improved hyperglycaemia may also be related to prolactin levels." (PMID 38918525, 2024). "However, contrary to our hypothesis, PRL actions were not involved in the effects of sulpiride reducing hyperglycemia in obese mice, as the drug exerted its glucose-reducing actions in mice lacking prolactin receptors." (PMID 38635745, 2024). "Consistent with the worsening of hyperglycemia, pancreatic islet density, β-cell number, proliferation, and survival, as well as circulating insulin levels were reduced, whereas α-cell number and pancreatic inflammation were increased in the absence of PRL signaling." (PMID 33746901, 2021).
pancreatic cancer (21 papers, 1990 to 2026). "Key pathways included those related to cancer, MAPK, PI3K-Akt, prolactin, and C-type lectin receptor signaling, as well as pathways associated with hepatitis B, endocrine resistance, toxoplasmosis, and pancreatic cancer." (PMID 41496007, 2026). "These pro-cancer effects of PRL were counteracted by some antipsychotic drugs like penfluridol in pancreatic cancer mouse models." (PMID 38273295, 2024). "In preclinical studies with pancreatic cancer, we identified a small molecule Penfluridol to inhibit PRL induced JAK/STAT activation by competitively binding to PRLR." (PMID 36714582, 2022). "We also found alteration in AGE-RAGE signaling pathway, insulin resistance signaling pathway and prolactin signaling pathway, which were less discussed in pancreatic cancer." (PMID 31795960, 2019). "Pancreatic cancer patients displayed increased levels of prolactin (PRL)." (PMID 38273295, 2024). "The authors observed 3-4 times greater prolactin levels in women with PDAC, which led us to investigate the role of PRL and PRLR in pancreatic cancer." (PMID 36714582, 2022). "However, its role in pancreatic cancer has not been discussed before and we report the involvement of prolactin signaling in pancreatic ductal adenocarcinoma, for the first time." (PMID 31795960, 2019).
Parkinson disease (20 papers, 2018 to 2025). A progressive degenerative disorder of the central nervous system characterized by loss of dopamine producing neurons in the substantia nigra and the presence of Lewy bodies in the substantia nigra and locus coeruleus. "On the other hand, PRL dysregulation has been associated with neurodegenerative diseases, including Huntington’s, multiple sclerosis, Alzheimer’s (AD), and Parkinson’s diseases (PD)." (PMID 40806464, 2025). "Dopamine, a common neurotransmitter that causes Parkinson’s disease, can bind to type-2 dopamine receptors to inhibit prolactin secretion." (PMID 36555554, 2022). "Furthermore, it has been observed that, while aging, PRL levels fluctuate, and that both increases and decreases in these concentrations have been linked to neurodegenerative diseases (including Huntington’s, multiple sclerosis, Alzheimer’s, and Parkinson’s)." (PMID 40806464, 2025). "Lisuride is a preferential dopamine D2 receptor agonist that inhibits prolactin secretion and reduces hyperprolactinemia in patients with Parkinson's disease (PD)." (PMID 40670864, 2025). "The FDA-approved dopaminergic medication cabergoline (Dostinex®) is a potent D2R agonist (Ki=0.7) that is used in the treatment of high prolactin levels, Parkinson’s disease, ovarian hyperstimulation syndrome, Cushing’s disease, and restless legs syndrome." (PMID 40346068, 2025). "Returning to the pilosebaceous unit, where seborrhoea was reported in patients with Parkinson’s Disease over half a century ago and reportedly responded to treatment with levodopa, the role of PRL in sebaceous gland biology has received little attention." (PMID 39000207, 2024). "Clinical studies have shown that the concentration of PRL is elevated in the serum of patients with Parkinson’s disease and in the cerebrospinal fluid of patients with Alzheimer’s disease with low Aβ1-42 levels." (PMID 38755517, 2024). "Most significantly, the first indications that PRL may actually influence cutaneous physiology were generated from observations in patients with Parkinsonism with seborrhoea, including those with the post-encephalitic form following the last global pandemic." (PMID 39000207, 2024). "Although the robustness of the findings is best left to be desired, the rs1799732 polymorphism has been reported to be associated with several side effects of antipsychotics: tardive dystonia, tardive dyskinesia, and parkinsonism, prolactin elevation, weight gain." (PMID 35893053, 2022). "While some studies have found more extrapyramidal side effects and elevated prolactin with high-dose SGA treatment than with standard doses, others have even reported less parkinsonism and fewer dropouts due to AEs." (PMID 38255270, 2024). "However, some studies have shown that patients with Parkinson’s disease have higher PRL levels, possibly because of the degeneration of dopaminergic neurons in Parkinson’s disease, and trihexyphenidyl, as an oral anticholinergic drug, does not cause an increase in PRL levels." (PMID 40964426, 2025). "Here, we report preclinical evidence that TAK‐063 may be beneficial as combination therapy with current antipsychotics without effects on plasma prolactin levels and cataleptic responses, which may be indicative of propensity to cause EPS such as drug‐induced Parkinsonism." (PMID 29417763, 2018).
adenomyosis (19 papers, 2013 to 2025). The growth of endometrial tissue inside the muscular wall of the uterine corpus. "By further demarcating cells into subclusters and investigating their changes under pathological conditions, we identified hyperactivation of prolactin (PRL) signaling as a major pathogenic driver of adenomyosis." (PMID 40804233, 2025). "Several animal models have shown increased uterine concentrations of PRL to be a risk factor for adenomyosis." (PMID 36967761, 2023). "Prolactin and its receptors are increased in adenomyotic tissue, suggesting an association between prolactin and adenomyosis." (PMID 37834773, 2023). "Further investigations are necessary to characterize the signaling pathways underlying the local prolactin production in adenomyosis." (PMID 35956024, 2022). "In addition, treating human endometrial stromal hEM15A cells with PRL induced the expression of a group of inflammatory cytokines associated with adenomyosis,33 suggesting that PRL signaling contributes to enhanced inflammatory responses in fibroblasts." (PMID 40804233, 2025). "PRL treatment of endometrial fibroblasts increased inflammatory cytokine production, establishing the important role of hyperactivation of PRL signaling in the stromal inflammation associated with adenomyosis." (PMID 40804233, 2025). "Additionally, an increase in prolactin concentration has been suggested as a potential risk factor for the pathogenesis of adenomyosis." (PMID 40004951, 2025). "In murine uteri, minimal elevation of serum PRL was sufficient to cause adenomyosis." (PMID 36967761, 2023). "Whether PRL can be considered as a single causal agent in inducing adenomyosis in humans is unclear." (PMID 35330066, 2022). "In addition, aged female mice deficient in DRD2 developed uterine adenomyosis spontaneously in response to prolonged PRL exposure." (PMID 35330066, 2022). "We further demonstrated the pathogenic effects of enhanced PRL-PRLR signaling in animal models and conducted a proof-of-concept study using an antibody targeting PRLR for the treatment of adenomyosis." (PMID 40804233, 2025). "In this study, we have shown, for the first time, that increased PRL is sufficient to trigger adenomyosis in PRL-TG mice." (PMID 40804233, 2025). "By 6 months, all UPT model mice had developed adenomyosis, whereas only a minority of RPT model mice had pathological changes, underscoring the critical role of localized PRL signaling in adenomyosis pathogenesis." (PMID 40804233, 2025). "Over 80% of the PRL-TG mice had developed adenomyosis by 12 months of age, whereas their wild-type (WT) littermates exhibited normal uterine structures, indicating that enhanced PRL signaling is sufficient to trigger adenomyosis development." (PMID 40804233, 2025). "Pathological PRL hyperactivation was further validated in preclinical animal models, where transgenic overexpression of PRL or pituitary transplantation induced an adenomyosis phenotype." (PMID 40804233, 2025). "Using single-cell RNA sequencing (scRNA-seq) of uterine samples from patients, we identified prolactin (PRL) signaling as a key pathological driver of adenomyosis." (PMID 40804233, 2025). "Taken together, overactivated PRL-PRLR signaling constitutes a major mechanism underlying the development and progression of adenomyosis." (PMID 40804233, 2025). "Using animal models, we demonstrated that increased PRL signaling was sufficient to induce adenomyosis, while blocking the PRLR markedly ameliorated adenomyosis manifestations." (PMID 40804233, 2025). "It has been reported that the upregulation of prolactin synthesis in adenomyosis takes place in the same manner as in the normal endometrium." (PMID 39407928, 2024). "Studies on mice models have shown the induction of adenomyosis by intrauterine pituitary isografts and after treatment with dopamine antagonists, suggesting the role of prolactin in the development of adenomyosis." (PMID 39407928, 2024).
adenomyosis (continued). "PRL directly influences the myometrium and induces adenomyosis by the degeneration of smooth muscle cells; however, the mechanisms still await further delineation." (PMID 39201621, 2024). "Since ovariectomy effectively removes the major source of estrogens and since estrogen is reported to further increase PRL release in mice with ectopic pituitary graft, this seems to suggest an indispensable role of estrogens in PRL-induced adenomyosis." (PMID 35330066, 2022). "Although PRL-induced adenomyosis has been reported in several mouse strains, such as SHN, SLN, Balb/C, C57, C3H, Balb/C and C3H F1 hybrids, C57, and ICR, and also in rats, so far there have been no epidemiological data in support for such a link in humans." (PMID 35330066, 2022). "We detected the upregulation of prolactin secretion in adenomyosis in the same pattern as in the normal endometrium, mediated by both cAMP and progesterone." (PMID 35956024, 2022). "Progesterone and cAMP upregulated prolactin secretion in adenomyosis in the same pattern as in the normal endometrium." (PMID 35956024, 2022). "A possible role for PRL in adenomyosis was derived initially from an experiment conducted over 40 years ago wherein hypophyseal transplantation into mice uteri induced adenomyosis." (PMID 35773139, 2022). "Dysregulation of prolactin signalling was also enriched in eutopic endometrium and in the myometrium of women with adenomyosis." (PMID 35773139, 2022). "DRD2 agonists have been shown to suppress PRL-induced adenomyosis and also have therapeutic potential for reducing pain and treating adenomyosis, likely through the promotion of the long isoform of PRLR (PRLR-L) and the inhibition of angiogenesis by DRD2." (PMID 35330066, 2022). "Consistently, SHN mice treated with dopamine antagonists, which resulted in increased PRL release, also developed adenomyosis." (PMID 35330066, 2022). "In the present study, several members of the PRL signalling pathway that are dysregulated in the endometrium of women with adenomyosis and are involved in cell proliferation, cell cycle progression and gluconeogenesis." (PMID 35773139, 2022). "Treatment of rats for 90–100 days with fluoxetine hydrochloride, a selective serotonin reuptake inhibitor (SSRI) that can increase the PRL secretion, induced adenomyosis with high incidence in rats." (PMID 35330066, 2022). "The effect of prolactin is unclear in the pathogenesis of adenomyosis but prolactin and its receptors seem to increase in adenomyotic tissue which suggests an association between the hormone and the disease." (PMID 34362193, 2021). "Franciyanc and colleagues investigated the level of sex hormones, prolactin and sex-steroids-binding globulin in the tissue of adenomyosis and uterine fibroids in the independent and combined development of pathologies." (PMID 30775685, 2018). "In this study, the CA125 and PRL levels were correlated with adenomyosis and declined significantly following PMWA." (PMID 25942631, 2015). "Furthermore, we demonstrated that localized PRL excess was more potent than systemic PRL elevation in driving adenomyosis." (PMID 40804233, 2025). "In summary, we identified PRL-PRLR signaling as a major pathological driver of adenomyosis." (PMID 40804233, 2025). "Notably, this ECM-high subcluster expanded with disease progression and showed exaggerated PRL signaling in adenomyosis patients." (PMID 40804233, 2025). "Importantly, we demonstrated that dysregulation of local PRL signaling led to the development and progression of adenomyosis, whereas inhibition of PRLR with the monoclonal antibody HMI-115 markedly ameliorated pathological manifestations." (PMID 40804233, 2025). "PRL signaling is overactivated in this epithelial subcluster, promoting cellular survival and proliferation, which contributes to lesion formation and expansion in adenomyosis." (PMID 40804233, 2025).